EGFR (epidermal growth factor receptor)
Diseases named in the same sentence as EGFR in open-access papers (continued):
Sharing a sentence is not in itself a finding about the gene and the disease.
tumor (continued). "EGFR is a driver of cell cycling and proliferation in GBM and other tumor types." (PMID 36130485, 2022). "Hence, we evaluated the potential role of EGFR, MAP2K1, mTOR, and YAP1 in promoting the infiltration of tumor immune cells within the TME." (PMID 35655775, 2022). "Recent studies demonstrated that EGFR-TKI could promote T cell infiltration, decrease the ratios of tumor-infiltrating Treg and M2-like macrophage, and improve the responsiveness to α-PD-1/PD-L1 in EGFR-mutated models." (PMID 35062949, 2022). "In addition, NIR-PIT targeting EGFR with anti-can225-IR700 resulted in rapid cell death in vitro and tumour growth inhibition in vivo, improving mouse survival." (PMID 35057796, 2022). "Interestingly, both EGFR and PI3K/AKT signaling pathways have been shown to induce NRF2 activation and tumor cell proliferation." (PMID 35806042, 2022). "In conclusion, these data indicate that visfatin SNPs may help to predict tumor staging in LUAD, especially in patients with EGFR wild-type status." (PMID 36429891, 2022). "Therefore, the tumor targeting and penetration of these tailored nanoparticles, particularly miR-125 + Afa/SLN-KL, in GC cells were increased by EGFR-directed L peptide and the subsequent ligand-mediated endocytosis." (PMID 36145507, 2022). "Although EGFR docking with Sdc4 in the tumor cells is required, cell cycle progression does not depend on EGFR kinase." (PMID 35569509, 2022). "We then explored the role of ARF6 in tumor growth and found that knocking down ARF6 significantly inhibited the proliferation of WT EGFR cells, A549 cells, and MDA-MB-231, as well as EGFR mutant cells, PC9 and H1975 cells." (PMID 36224181, 2022). "Both, EGFR signaling and EMT are central regulators of tumor progression in HNSCC." (PMID 36076232, 2022). "Current research revealed that epidermal growth factor receptor (EGFR) reinforced CD44-mediated TNBC cell clustering, whether blockade of EGFR has synergistic effects on erastin-induced tumor inhibition of CSC clusters is still poorly understood." (PMID 35725558, 2022). "The use of chemotherapy in combination with EGFR-TKI may efficiently kill the proliferative cells, while sustaining the rest of the tumour cells in dormancy." (PMID 35681591, 2022). "So, the inflammatory environment in tumor tissues could be mediated by EGFR via NF-κΒ and STAT3, and the blocking of EGFR signaling can suppress the promotion of tumor inflammations." (PMID 36438839, 2022). "In addition, we detected the levels of tumor biomarkers in LUAD and found that the levels of TMED2, CEA, NSE, and EGFR in the sh-TMED2 group were reduced (P < 0.05)." (PMID 35135563, 2022). "CAR T cell-derived exosomes exhibit excellent capability for use as direct aggressors in immunotherapy, since ex vivo-produced human exosomes transporting human EGFR and HER2-specific CAR have powerful in vivo activity against EGFR+ and HER2+ human tumor cells in xenograft models." (PMID 35269412, 2022). "In this study coimplanted luciferase-labeled EGFR- tumor cells decreased within the tumors of EGFR TcE treated animals but not in animals treated with an irrelevant TcE." (PMID 36159851, 2022). "Notably, NK1R is co-expressed with epidermal growth factor receptor (EGFR) in NSCLC patients’ tissues and co-localized in the tumor cells." (PMID 35013118, 2022). "Determining how EGFR upregulates TERT specifically from the mutant TERTp is, therefore, critical for understanding the potential interaction between oncogene signaling, cell proliferation, and tumor cell immortality at the molecular level." (PMID 36130485, 2022).
tumor (continued). "In our cohort, after adjusting for patient characteristics, treatments, and other tumor genetic alterations, we observed that while CDKN2A and CDKN2B deletions were associated with worse survival, EGFR amplification was not correlated with poor outcomes." (PMID 36380219, 2022). "Moreover, miR-30b can inhibit the PI3K/AKT signaling pathway through the regulation of EGFR, AKT, Derlin-1, GNA13, SIX1, and other target genes, thus inhibiting the EMT process of tumor cells and promoting apoptosis." (PMID 35291564, 2022). "Small-molecule inhibitors or monoclonal antibodies of targeted therapy, such as inhibitors for epidermal growth factor receptor (EGFR), transforming growth factor (TGF)-β, BRAF, VEGF, and MYC, can produce impressive tumor responses in selected patients while having potentially fewer side effects." (PMID 36119019, 2022). "Another therapeutic possibility could be addressed by the combined inhibition of EGFR and IGF-IR, which could lead to a reduction in tumor volume." (PMID 35956111, 2022). "In addition, we also found that overexpression of EGFR and SHC1 promoted the expression of tumor-related transcription factors." (PMID 35706930, 2022). "Liquid biopsy is useful in detecting tumor heterogeneity, particularly when diverse resistance mechanisms develop in different tumor sites, as reported in the case of an NSCLC with an EGFR exon 19del and T790M, which had a liver progression with an acquired CCDC6-RET fusion." (PMID 35454838, 2022). "It is thus tempting to speculate that an RTK spectrum beyond ERBB3, EGFR, and AXL might be affected by SLC35B2 levels, depending on individual tumor type and treatment context." (PMID 35798875, 2022). "Anti-EGFR CAR-T cells were incubated with KYSE150-luci, KYSE450-luci, or KYSE30-luci cells and the lytic activity of the effector cells was assessed based on the luciferase expression in the tumor cells." (PMID 36551506, 2022). "Collectively our results suggested that EGFR, MAP2K1, mTOR, TEAD1, and YAP1 could mediate invasive tumor phenotypes and worsen prognoses via mechanisms involving both T-cell exclusion and dysfunctional phenotypes." (PMID 35655775, 2022). "Despite anti-EGFR therapy, the sustained activation of the PI3K/Akt pathway might be explained by looking at the genetic background of the resistant tumor." (PMID 36551613, 2022). "HER2, EGFR, BRAF) are overexpressed in a fraction of tumor samples where their inhibition may show efficacy." (PMID 35433463, 2022). "Moreover, to overcome the poor tumor selectivity of traditional nanoparticles, we carried the monoclonal antibody CTX on the surface of the INPs, which can effectively recognize EGFR." (PMID 35242698, 2022). "First, EGFRvIII-expressing cells drive the growth of EGFR amplified cells through secretion of cytokines and growth factors, thus there is not a strong selection for EGFRvIII cells in the whole tumour." (PMID 36497413, 2022). "Hence, some EGFR-mutant NSCLC patients exhibit a particularly good prognosis with a time to progression exceeding 30 months, while others are diagnosed as having tumor progression within 6 months of EGFR-TKI treatment initiation." (PMID 36139605, 2022). "If this is not the case, the tumor will abrogate surface expression or express an epitope-disrupted but still functional receptor as has been previously shown for EGFR antibodies and CD19-targeting cell therapies." (PMID 35936668, 2022).
tumor (continued). "Downregulation of MMP9, EGFR, VEGFR and STAT3 in HepG2 cancer cells could appear to play a role in tumor invasion and angiogenesis and to mediate the tumor microenvironment." (PMID 36284117, 2022). "Except for EGFR expression, other tumor markers were not statistically different between the 2 curvatures." (PMID 35984169, 2022). "Tumour cells were stained strongly with VIM, EGFR, and Bcl-2." (PMID 35906487, 2022). "Furthermore, sex, tumor depth, lymph node status, high FAP expression, and high EGFR expression were significant prognostic factors for DFS." (PMID 36418422, 2022). "However, a growing number of evidence show that ligand activation of GPCR can also induce transactivation of EGFR in various cancer cells, which represent an important mechanism of regulating both GPCR- and EGFR-mediated tumor progression." (PMID 35013118, 2022). "Moreover, dasatinib inhibited the progression of the HuCCT1 tumor on SCID mice skin coupled with decreasing the expression of Hic-5 and EGFR and the activities of Src, AKT and JNK." (PMID 36559193, 2022). "RBM10 deficiency does not modulate the oncoprotein target itself (here, mutant EGFR), but instead functions via the differential regulation of the apoptotic machinery in tumor cells." (PMID 35579943, 2022). "Interestingly, the epidermal growth factor receptor (EGFR) family can also be activated, and bile acids induce the overexpression of ERBB2 (HER2) in the tumor tissue contacted, leading to a significantly worse prognosis." (PMID 35406597, 2022). "Collectively our results suggested that EGFR, MAP2K1, mTOR, TEAD1, and YAP1 could mediate invasive tumor phenotypes and produce worse prognoses via mechanisms involving both the T-cell exclusion and dysfunctional phenotypes." (PMID 35655775, 2022). "Cetuximab is a monoclonal antibody against epidermal growth factor receptor that blocks downstream signaling pathways of receptor tyrosine kinases, including Ras/Raf/MAPK and PI3K/Akt, thereby inhibiting tumor cell proliferation and inducing cancer cell apoptosis." (PMID 36387129, 2022). "Contrary to the observed contrast, without EGFR target binding a higher uptake in lung than in tumor was predicted for afatinib." (PMID 35890095, 2022). "Mutation of KRAS bypasses EGFR signalling, nullifying anti‐EGFR‐targeted therapy and so patients with CRC tumours harbouring mutant RAS do not generally receive anti‐EGFR therapy." (PMID 34856074, 2022). "Like in other cancers, EGFR is active in many GBM and controls tumor formation and angiogenesis." (PMID 35163279, 2022). "Fourthly, tumor mutation-driver genes such as EGFR, ALK, and ROS1 and the use of targeted therapies were not recorded in the SEER data, and reflecting the time period of this study, neither were tumor PDL-1 status and the use of immunotherapy." (PMID 35847910, 2022). "In HCC cells, the epidermal growth factor receptor (EGFR)‐P38 MAPK axis enhanced the aerobic glycolysis in HCC cells, which may stimulate tumor immunosuppression." (PMID 36119533, 2022). "This correlation in protein levels was also observed in tumor cells from cases lacking activating EGFR amplifications." (PMID 35973991, 2022). "Tumor, node, metastasis (TNM) stage 3 + 4 primary NSCLC is positive for TMEM16A and EGFR." (PMID 35205604, 2022). "Whether that EGFR inhibition impedes formation of ECM-detached cell clusters, enhances autophagy and achieves the purpose of tumor inhibition via ferroptosis remains to be explored." (PMID 35725558, 2022). "The average expression levels, presented as transcripts per million (TMP) in tumor and non-tumor tissues, were 38.4 and 20.4, respectively, suggesting upregulated expression of EGFR in ESCC tumor tissues." (PMID 35163685, 2022). "Finally, we also detected the levels of tumor biomarker levels in LUAD and found that the expression of TMED2, CEA, NSE, and EGFR in sh-TMED2 mice was reduced (P < 0.05), consistent with the in vitro results." (PMID 35135563, 2022).
tumor (continued). "Besides, the expressions of CXCL12-CXCR4, EGFR-MIF, FGFR1-FGR7, MIF-TNFRSF14, and WNT5A-PTPRK were predicted in the cross-talk between CAFs and tumor cells." (PMID 35784460, 2022). "Epidermal growth factor receptor (EGFR) is a receptor tyrosine kinase of the ErbB family (which also includes HER2, HER3 and HER4), and its overexpression has been reported in several human and canine tumours." (PMID 35324835, 2022). "A total of 22.4% patients did not have tumor evaluation because of rapid progression of tumor or patients’ fragility after the initiation of EGFR-TKIs." (PMID 35158940, 2022). "For EGFR, expression was determined in 88 (92.6%) patients: of these, none were considered positive because there was no membrane staining of any tumor cells." (PMID 36358811, 2022). "EGFR phosphorylates ELK1 through the MEK/ERK pathway, which can activate GDH1 transcription and glutamine degradation, providing a new perspective for changes in glutamine metabolism in tumor cells." (PMID 36034789, 2022). "We observed superior tumor targeting in the KYSE520 xenograft model compared to the KYSE150 xenograft model, which may be due to the high expression of EGFR in KYSE520 cells." (PMID 35416106, 2022). "EGFR directed PET biomarkers will de facto never be able to diagnose an activating EGFR mutation, as this requires tumor DNA sequencing on tumor tissue or liquid biopsies." (PMID 36313723, 2022). "Moreover, oral administration of musarin for 14 days reduced tumor xenograft in NOD/SCID mice in vivo, and its effectiveness was comparable to that of gefitinib, the representative EGFR inhibitor." (PMID 36359361, 2022). "Studies at home and abroad have found that cyclooxygenase-2 (COX-2), Ki67, vascular endothelial growth factor (VEGF), CD44V6, epidermal growth factor receptor (EGFR), double microsome 2 (MDM2) and transforming growth factor TGF-β1 have certain clinical significance in tumor growth." (PMID 36384712, 2022). "Even though there are many nanosystems targeting the EGFR pathway with applications in neoplasia, they are lacking in the field of cardiology." (PMID 35456545, 2022). "Since EpCAM and EGFR act on epithelial cells, no expression of these proteins is found in LNs without tumor." (PMID 36581931, 2022). "Similar to a previous study, we also demonstrated that miR-491-5p inhibits the expression of Epidermal Growth Factor Receptor (EGFR), whose spontaneous activation in the absence of ligand is associated with tumor progression." (PMID 35337159, 2022). "Although the mechanism responsible for the slight difference in effects between MSC-derived exosomes and MSC’s conditioned media is unclear, this study clarified that exosomes act against tumor development through reducing the expression of AQP5 and EGFR cell surface receptors." (PMID 36114463, 2022). "Furthermore, SLUG colocalized with EGFR and pEMT marker LAMC2 in selected patients with a homogeneous or a peripheral SLUG expression at the edges of tumor areas." (PMID 34382739, 2022). "There was a negative correlation between CD73 and EGFR bulk mRNA levels in the full 102 tumor CBTTC cohort, in keeping with the relative absence of gene amplification events." (PMID 35973991, 2022). "Without EGFR molecular targeting, no anti‐tumor effect was observed and desmoplasia remediation was significantly less pronounced." (PMID 35748165, 2022). "As described in the results section, our drug resistant PDX model retained EGFR overexpression from the original tumor but not EGFR gene amplification." (PMID 36338758, 2022).
tumor (continued). "SEC61G expression significantly positively correlated with EGFR in HNSC tumor but not in HNSC normal." (PMID 36712687, 2022). "Similarly, IONPs induce elevation in MSC EGFR and this supports MSC tumour tropism (towards tumour EGF)." (PMID 35103937, 2022). "After nearly 8 weeks of oral administration of the third-generation EGFR-TKI aumolertinib (110 mg/day) started in February 2021, imaging showed significant tumor regression, lesion volume reduction to 2.2 × 2.0 × 1.8 cm, partial remission (PR), and clinical stage reduction to stage IB (T2N0M0)." (PMID 35425698, 2022). "In this study, mutations in the genes ARID1A, APC, ERBB4, NCOR1, PDGFRA, ATM, and CDKN2A were either non-recurrent or of very low frequency, while none of the 14 sequenced EP tumours harboured mutations in the genes HRAS, EGFR, or RB1." (PMID 34045664, 2022). "The hub genes, including PIK3R1, CTNNB1, JUN, EGFR, and APP, might play an important role in tumor development." (PMID 35733630, 2022). "Moreover, metabolites have been shown to carry signals and stimulate oncogenic pathways and tumor microenvironment (TME) components such as fibroblasts, facilitating resistance to EGFR TKIs in various ways." (PMID 35203491, 2022). "A treatment with EGFR TKIs for patients who suffered from NSCLC prolonged their survivability, but the consequences for the tumor environment after such a treatment remain unclear." (PMID 35745666, 2022). "Activating mutations in epidermal growth factor receptor (EGFR) have been found in approximately 50-60% of Asian female patient, and this non-smoking female patient refused genetic testing of the tumor." (PMID 36408132, 2022). "It has been demonstrated that the expression of biomarkers such as KRAS, NRAS, and BRAF, in conjunction with the MSI state of the tumour, serves as a negative predictor for anti-EGFR therapy in mCRC patients." (PMID 36612217, 2022). "Next, we analyzed whether early tumor shrinkage (ETS) predicts PFS and OS, as previously reported for anti-EGFR based treatment." (PMID 36605436, 2022). "We analyzed responses to inhibitors of ERBB family receptor tyrosine kinases (RTKs) that have been previously shown to drive tumor progression in the KL GEMM, and found that only pan-ERBB inhibition increased the survival of ASCi.v. mice compared to control or single ERBB1/EGFR inhibition." (PMID 36355420, 2022). "Therefore, both the murine and human BsAb bound simultaneously to CD3 on ATC and EGFR on tumor cells, and BsAb armed ATC were capable of binding to murine CT26 and human HT29 EGFR expressing CRC tumors." (PMID 35177811, 2022). "Differences in 89Zr-panitumumab uptake occurred in the tumor tissue between the blocking and non-blocking groups demonstrating the specificity for EGFR." (PMID 36357495, 2022). "All tumor clusters expressed CK7/CK19 but different levels of ER, EGFR, and CK8." (PMID 35243422, 2022). "The loss of PTEN results in cancer cells resistance for EGFR inhibitors, such as erlotinib, that initiates negative regulation in the PI3K-AKT pathway leading to PI3K activation and tumor progression." (PMID 35163777, 2022). "In addition, MHCI and class II molecules were enhanced after exposure to EGFR-TKIs, which will always be accompanied by the induction of IFN-γ and T-cell–mediated tumor killing." (PMID 35734411, 2022). "This somatic mutation in the B-RAF gene generates high proliferation and antiapoptotic behavior in the tumor cell, because, as with the RAS mutation, RAF is continuously activated in the absence of stimuli further up the cascade near EGFR and RAS." (PMID 36005935, 2022).